PDGFD (platelet derived growth factor D)
Diseases named in the same sentence as PDGFD in open-access papers (continued):
Sharing a sentence is not in itself a finding about the gene and the disease.
sarcoma (1 paper, 2021). A usually aggressive malignant neoplasm of the soft tissue or bone. "In the non-GIST sarcoma cohort, histological subtype, location, grade, tumor size, PDGFA and PDGFD expression levels were introduced in the multivariate model." (PMID 33524869, 2021).
soft tissue sarcoma (1 paper, 2024). A malignant neoplasm arising from muscle tissue, adipose tissue, blood vessels, fibrous tissue, or other supportive tissues excluding the bones. "Additionally, a study examining the expression levels of PDGF ligands and receptors in 255 patients with soft tissue sarcoma discovered that high levels of PDGFD were associated with a decreased risk of metastasis in both univariate and multivariate analyses." (PMID 38652223, 2024).
teratoma (1 paper, 2022). A non-seminomatous germ cell tumor characterized by the presence of various tissues which correspond to the different germinal layers (endoderm, mesoderm, and ectoderm). "Genetic deletion of Pdgfd in mice impaired blood vessel formation in both embryonic development and teratoma growth, and overexpression of PDGFD-induced ESC differentiation towards EC lineage." (PMID 35859222, 2022). "Importantly, genetic deletion of Pdgfd in mice decreased cardiac blood vessel density in both embryonic and neonatal mice, and PDGFD knockdown in ESCs decreased blood vessel density during teratoma formation." (PMID 35859222, 2022).
tumor (85 papers, 2008 to 2026). "CCA cells release platelet-derived growth factor D (PDGF-D) causing CAFs to recruit in the close area of the tumor tissue." (PMID 39156971, 2024). "High tumor expression of PDGFD was associated with a poor BLCA prognosis compared with those BLCA patients with low tumor expression of PDGFD." (PMID 34858395, 2021). "Nevertheless, ERK activation by PDGFRβ signaling pathway cannot compensate the loss of HIF1α-PDGFD-PDGFRα-AKT network for GBM tumor growth because knockout of either HIF1A or PDGFD or PDGFRA in U251 cells eradicated the tumor growth." (PMID 34470658, 2021). "In contrast, when BLCA tumors were stratified for low PDGFD expression, a high tumor abundance of IL2NK was associated with improved prognosis, whereas the SPANK was associated with poor prognosis and to a lesser extent the ReNK." (PMID 34858395, 2021). "Similar to TCGA, these results show that high tumor expression of PDGFD is associated with poor CGGA LGG prognosis, and tumors enriched for the SPANK and memory CD8+ T cell phenotypes have improved prognosis." (PMID 34539622, 2021). "High tumor abundance of the SPANK was associated with improved prognosis when LGG tumors were stratified for the expression of PDGFD in both TCGA and CGGA patient cohorts." (PMID 34539622, 2021). "Similar to TCGA LGG patient cohort, high tumor expression of PDGFD in CGGA LGG patients was associated with a poor prognosis." (PMID 34539622, 2021). "Overall, these data show that a high tumor expression of PDGFD is associated with the activation of core cancer hallmarks and poor BLCA patient prognosis." (PMID 34858395, 2021). "Interestingly, when BLCA tumors were stratified for PDGFD expression and each respective NK cell phenotype, a high tumor abundance of the SPANK phenotype was associated with a poor BLCA prognosis." (PMID 34858395, 2021). "Finally, using CIBERSORT, we have uncovered an intriguing association between tumor expression of PDGFD and tumor enrichment of the SPANK and T helper and memory CD8+ T cell signatures, that may be important for LGG patient survival." (PMID 34539622, 2021). "Conversely, platelet-derived growth factor-D (PDGF-D) is primarily derived from the tumor cells, which activates RAC1/CDC42 and JNK pathways within CAFs, thereby stimulating their activation and migratory capacity." (PMID 41445734, 2025). "Recently an important study showed that PDGFD can inhibit tumor growth by inducing immunoreceptor tyrosine-based activation motif (ITAM) signaling via NKp44, a NK cell receptor, which leads to the generation of anti-tumoral factors from NK cells." (PMID 37790751, 2023). "We can find that the expression of GNG7, MXRA7, ASB2, and PDGFD in tumor samples is significantly lower than that in normal samples, while the expression of RPS6KA1, CHMP4C, APOL1, and LYPD3 is reverse." (PMID 36225190, 2022). "Transforming growth factor β (TGF-β) and platelet-derived growth factor D (PDGF-D) secreted by tumor epithelial cells recruit CAFs." (PMID 35433771, 2022). "The coexpression genes of PDGFD were proved to be mediated in many tumor pathways, including the PI3K-Akt signaling pathway and proteoglycans." (PMID 35509844, 2022). "C14 and C25 possessed FGF7, IGFBP4, and PDGFD paracrine functions, further promoting tumor growth and differentiation to the proliferative stage." (PMID 35664733, 2022). "Since protumorigenic pathways associated with PDGFD expression were enriched in BLCA, we next determined the relationship between tumor expression of PDGFD or PDGFRB and BLCA patient prognosis." (PMID 34858395, 2021). "Activation of natural killer (NK) cell function is regulated by cytokines, such as IL-2, and secreted factors upregulated in the tumor microenvironment, such as platelet-derived growth factor D (PDGF-DD)." (PMID 34858395, 2021). "LGG patients with low tumor expression of PDGFD had more favorable prognosis compared to LGG patients with high tumor expression of PDGFD." (PMID 34539622, 2021).
tumor (continued). "Overexpressed platelet-derived growth factor-D (PDGF-D) normalizes tumor vessels by enhancing perivascular coverage, thereby facilitating anti-cancer drug delivery and efficacy." (PMID 24091497, 2014). "The platelet-derived growth factor-D (PDGF-D) was demonstrated to be able to promote tumor growth and invasion in human malignancies." (PMID 24646915, 2014). "Studies have indicated that PDGFD promoted cell proliferation by increasing DNA binding capacity of NF-κB and down-regulation of PDGFD inhibit tumor invasion through inactivation of Notch-1 and NF-κB signaling." (PMID 25108500, 2014). "It was found that expression of IGF1, HGF, PDGFC, and PDGFD were significantly increased 5.32-, 10.21-, 6.24-, and 3.24-fold in tumor tissues, respectively, when compared with arachnoidal tissue by qRT-PCR." (PMID 23285163, 2012). "Additionally, interfering with the HIF1α-platelet-derived growth factor D (PDGFD)-PDGF-receptor α (PDGRα)-AKT impairs the feedforward loop of HIF1α perpetuation in the hypoxic tumor core." (PMID 39859381, 2025). "Moreover, we used IHC to investigate the expression levels of classic tumor biomarkers, including PDGFD, Ki-67, E-cadherin, N-cadherin, and β-catenin." (PMID 37253627, 2023). "Concerning HCC, it has been confirmed that the platelet-derived growth factors (PDGF, including PDGFA, PDGFB, PDGFC, and PDGFD) participate in modulating the tumor development and chemoresistance by interacting with its receptor PDGFR and activating the downstream signaling pathway." (PMID 36463115, 2022). "Western blot was selected to determine the expression level of PDGFD in normal and tumor tissues." (PMID 35509844, 2022). "In contrast, PDGFD expression was associated with numerous cancer hallmark pathways in BLCA tumors compared with normal bladder tissue, and a high tumor abundance of PDGFD transcripts and the PDGF-DD-activated NK cell phenotype were associated with a poor BLCA prognosis." (PMID 34858395, 2021). "Indeed, our analysis shows that LGG patients with high tumor expression of PDGFD had a poor prognosis in both TCGA and CGGA cohorts." (PMID 34539622, 2021). "In addition, it has also been reported that tissue-resident stem cells induce EMT through interaction with the TME via PDGFD, thereby leading to increased number of CSCs and tumor growth." (PMID 30227608, 2018). "However, the platelet-derived growth factor-D over-expression significantly promoted tumor growth and the invasion occurred both in vitro and in vivo." (PMID 27077853, 2016). "Paradoxically, the up-regulation of PDGFD in CIKIL-15 not only could promote the proliferation of CIKIL-15 cells but also promote tumor cells survival through cell and cell interaction in tumor cytotoxic assay." (PMID 25108500, 2014). "Given that the expression of PDGFD was primarily associated with pro-tumor pathways and poor prognosis, we further hypothesized that enrichment of the SPANK phenotype in LGG tumors may be associated with effective anti-tumor immunity and improved prognosis." (PMID 34539622, 2021). "Our results show that high tumor abundance of the IL2NK phenotype and transcripts for the KLRK1, CD160, and TNFRSF14 receptors are associated with improved survival, whereas high tumor abundance of the SPANK and PDGFD transcripts is associated with poor survival." (PMID 34858395, 2021). "Moreover, PDGFD has been found to regulate the EMT process that is important for tumor metastasis." (PMID 30227608, 2018). "Immunohistochemistry assessed PDGFD and PDGFRB expression, while multicolor immunofluorescence and flow cytometry provided insight into spatial relationships and the tumor immune microenvironment." (PMID 38652223, 2024). "Translocations in FOXO3/PDGFD and DDX10/SKA3 are interesting due to their possible role in tumor cell growth and survival." (PMID 36831263, 2023).
tumor (continued). "Additionally, we demonstrated that downregulation of PITPNA-AS1 could inhibit the tumor-promoting effect rescued by inhibiting miR-363-5p or overexpressing PDGFD, indicating that PITPNA-AS1 accelerates HCC development by downregulating miR-363-5p and upregulating PDGFD expression." (PMID 37253627, 2023). "In a recent syngeneic GBM mouse model, elevated PDGFD expression induced by mouse cytomegalovirus (MCMV) infection results in pericyte recruitment, angiogenesis, and enhanced tumor growth." (PMID 37058447, 2023). "The results showed that RPS6KA1, PDGFD, APOL1, and LYPD3 are all upregulated in tumor tissues, which were consistent with GEPIA2." (PMID 36225190, 2022). "Tumor size and PDGFA expression levels were identified as independent adverse prognostic factors (P = 1.3 × 10−4 and P = 4.3 × 10−2, respectively) while PDGFD expression levels were a favorable prognostic factor for metastasis-free survival (P = 4.99 × 10−3)." (PMID 33524869, 2021). "Tumor expression of TGFBI, IGFBP3, and CHI3L1 were positively correlated with PDGFD and PDGFRB expression in TCGA LGG dataset, respectively." (PMID 34539622, 2021). "Knockout of HIF1A, PDGFD or PDGFRA in U251 cells inhibits cell growth and invasion in vitro and eradicates tumor growth in vivo." (PMID 34470658, 2021). "Among the genes upregulated in the atypical tumor compared to the nevus were: SOX10, the receptor tyrosine kinases ROS1 and NTRK3, PLA2G2A, and HOXA11, while DUSP2, PDGFD, and ELN were downregulated." (PMID 35052351, 2021). "CMV-induced expression of platelet-derived growth factor D (PDGF-D) enhanced GBM growth by promoting pericyte recruitment and tumor angiogenesis." (PMID 32903717, 2020). "Interestingly, the switch in the expression levels of FGF1 and FGF2 (downregulated and upregulated in low-responder cells, respectively) as well as the upregulation of one member of the PDGF family (i.e. PDGFD) might be potentially driving the tumor progression in these GBM low-responder cells." (PMID 34316686, 2020). "It has been shown that platelets induce tumor angiogenesis by releasing platelet-derived growth factor D and VEGF, and subsequently promotes the tumor growth." (PMID 29677116, 2018). "It has been found that adipose tissue MSCs contribute to tumor-promoting state of TME, through increased secretion SDF-1, VEGF, chemokine ligand 5 (CCL5), platelet-derived growth factor D (PDGF-D), and TGF-β in response to presence of tumor cells." (PMID 27630452, 2016). "The ligand-receptor pairs IGF2-IGF1R, PDGFD-PDGFRB and PDGFC-PDGFRA were enriched between these two cell types, implicating Scissor+ tumor cells may play an important role in promoting expansion of CAFs." (PMID 40098972, 2025). "Activation of genes related to this pathway (CSF2, SERPINE1, PDGFD, CYFIP2, IL7R, MYB, CSF1) can promote tumor cell proliferation and survival, and may also affect immune cells in the TME." (PMID 41328768, 2025). "Similarly, ITGAV, PDGFC, PDGFD, and COL1A1—the most abundant collagen in human tissues—are often highly expressed in tumor cells, and inhibiting their expression can effectively suppress cell proliferation, migration, and invasion." (PMID 41227351, 2025). "Collectively, our data indicate that PITPNA-AS1 exerts tumor-promoting effects in HCC progression and that PITPNA-AS1/miR-363- 5p/PDGFD axis may be a good pharmaceutical target for HCC treatment." (PMID 37253627, 2023). "In contrast, the NCR NKp44 can bind to platelet-derived growth factor D (PDGF-DD), which is overexpressed by many solid tumors including BLCA, and may activate NK cell antitumor functions to control tumor growth." (PMID 34858395, 2021). "Higher LGG tumor expression levels of PDGFRB alone displayed a trend towards poor survival when PDGFD expression was low, but this was not statistically significant." (PMID 34539622, 2021).
tumor (continued). "Specifically, FGF2 is the main member of the FGF family implicated in cancer development and drug resistance, and PDGFD and its receptor (PDGFRB) have been recently defined as key drivers of tumor progression since a PDGFRB downregulation impairs immediately GBM progression (A.C.V.-B." (PMID 34316686, 2020). "Tumor stromal pathways are also in evidence with the common genes including; TLR4, TLR7, HLA-DRA, HLA-DQA1, CXCR4, FOS and TGFB2 (immune surveillance and chemokine pathways) and NF2, ITGA7, PGF, ITGA4, PDGFD and PARVA (focal adhesion)." (PMID 23226201, 2012). "Intriguingly, the prognostic value of PDGFs was dependent on the tumor vs. the stromal expression of the analyzed proteins, i.e., stromal PDGFD could predict CSS; in contrast, the tumor but not the stromal PDGFC could predict CSS." (PMID 33918816, 2021). "However, the relationship between PDGFD-PDGFRB and tumor immune microenvironment has not previously been reported." (PMID 38652223, 2024).
cancer (51 papers, 2010 to 2025). A tumor composed of atypical neoplastic, often pleomorphic cells that invade other tissues. "In contrast, upregulation peaks were observed on the gene locus and adjacent noncoding region of platelet-derived growth factor D (PDGFD) that is associated with the progression of various types of cancer, including AML." (PMID 40181449, 2025). "A high level of platelet derived growth factor D (PDGF-D) secreted from CCA cells promoted VEGF-C secretion from cancer-associated fibroblasts and enhanced lymphangiogenesis and LN metastasis." (PMID 34831316, 2021). "Associations of NRP2, NRP1 and several NRP ligands (i.e., PDGFC and PDGFD) that have been implicated in cancer progression were analyzed." (PMID 33918816, 2021). "Until now, research on PDGFD has concentrated on its association with diseases, especially cancers in humans." (PMID 25888314, 2015). "Deletions in or near prominent cancer-associated genes (for example, ALK, LIN28B, PDGFD and WNT7B) were also detected." (PMID 37188965, 2023). "The results showed that PDGFD had higher levels of expression in cancer tissues than normal tissues." (PMID 35509844, 2022). "Further evidence for the role of PDGFD as an effector molecule in cardiovascular diseases and cancer has been reviewed." (PMID 33971972, 2021). "Platelet-derived growth factor-D (PDGF-D) plays a crucial role in the progression of several cancers." (PMID 28035069, 2017). "We also identified two genes, thrombospondin I (THBS1) and PDGFD, which participate in a wide range of signaling pathways that regulate cellular processes involved in cancer genesis and progression." (PMID 27756408, 2016). "Many protumorigenic pathways associated with PDGFD expression that represent core cancer hallmarks were enriched in BLCA but not in normal bladder tissue." (PMID 34858395, 2021). "However, these cells maintain active the same VEGFA-activated pathways by the upregulation of others alternative TRK receptor ligands (i.e. FGF2, PDGFD and KITLG) that have been implicated in the development and drug resistance in other cancer types." (PMID 34316686, 2020). "Our identification of rs117361561 (maps to PDGFD), a novel uncommon SNV with a large effect size, is intriguing because PDGFD has a fundamental role in cell growth, differentiation, survival regulation, invasion, and angiogenesis, supporting its potential association with cancer progression." (PMID 35939300, 2022). "Platelet‐derived growth factor‐D (PDGF‐D) is expressed at high levels in various tumors and is involved in epithelial–mesenchymal transition (EMT) and the malignant behavior of cancer cells." (PMID 40530904, 2025).
cardiovascular diseases (3 papers, 2019 to 2023). "A cardiovascular disease risk study found that PDGFD promotes proliferation, migration, and inflammatory factor expression in cardiovascular adventitial fibroblasts." (PMID 37554505, 2023).
PDGFD also shares sentences with these, for which no sentence is quoted: colorectal cancer (7 papers); colon cancer (3); lung carcinoma (3); rheumatoid arthritis (3); brain tumor (2); Dermatofibrosarcoma (2); intracerebral hemorrhage (2); lung fibrosis (2); osteoarthritis (2); prostate tumor (2); pulmonary arterial hypertension (2); renal carcinoma (2); aneurysm (1); Anxiety (1); aortic aneurysm (1); aortic atherosclerosis (1); Ataxia (1); autism spectrum disorder (1); Brain atrophy (1); brain cancer (1); breast tumors (1); bronchopulmonary dysplasia (1); cardiac failure (1); cardiomyopathy (1); carotid atherosclerosis (1); chondrosarcoma (1); chronic obstructive pulmonary disease (1); colorectal tumors (1); crescentic glomerulonephritis (1); emphysema (1).
A further 35 diseases each share a sentence with PDGFD in 1 paper.